CTLA4 (cytotoxic T-lymphocyte associated protein 4)
Diseases named in the same sentence as CTLA4 in open-access papers (continued):
Sharing a sentence is not in itself a finding about the gene and the disease.
colon adenocarcinoma (24 papers, 2014 to 2026). "CTLA-4 ICB in preclinical murine models of colon adenocarcinoma significantly decreased tumour growth, increased the frequency of tumour-infiltrating effector T cells and selectively depleted intra-tumoural regulatory T cells." (PMID 35708739, 2023). "Agonistic CD27 monoclonal antibodies can be used to enhance the efficacy of depleting antibodies such as anti-CTLA-4 in a colon adenocarcinoma tumour model." (PMID 35288635, 2022). "Firstly, we explored the P407 hydrogel-based ICG-PDT combination with CTLA4 blockade therapy in the MC38 colon adenocarcinoma model." (PMID 35974207, 2022). "We treated B6/lpr mice with anti-PD-1 and anti-CTLA-4 antibodies in the setting of established MC38 colon adenocarcinoma." (PMID 33571254, 2021). "In a therapeutic treatment model of MC38 colon adenocarcinoma, monotherapy with either anti-CTLA-4 or anti-PD-1 was partially efficacious, with anti-PD-1 eliciting greater rates of tumor rejection." (PMID 27610613, 2016). "Second, accumulation of CCR4+CTLA-4+ regulatory T cells was found in colon adenocarcinomas as well as an increase in CTLA-4+ conventional T cells, susceptible to immune regulation in the tumor-associated mucosa." (PMID 26605342, 2015). "In particular, the human colon adenocarcinoma line SW480 was found to express CTLA-4 on the cell surface." (PMID 24822170, 2014). "MLKL deficiency in CT26 colon adenocarcinoma (without expression of an artificial antigen such as OVA) also resulted in strongly impaired antitumor activity of combined anti-PD-1/CTLA-4 ICI immunotherapy in tumor-bearing BALB/c mice." (PMID 40345706, 2025). "CTLA4 expression was elevated in colon adenocarcinoma (COAD), lung squamous cell carcinoma (LUSC), and prostate adenocarcinoma (PRAD) and reduced in thymoma (THYM)." (PMID 33072070, 2020). "However, the success rate of immune checkpoint inhibition is not ideal, and there are still abundant cancers refractory to CTLA-4 and PD-1 blockade, like colon adenocarcinoma (COAD)." (PMID 36081997, 2022). "We found that the efficacy of depleting mAb such as anti-CTLA-4 and anti-CD25 can be enhanced by CD27 mAb in a murine colon adenocarcinoma tumour model." (PMID 35288635, 2022). "In this study, we demonstrate that agonistic anti-mCD27 can also be used to enhance the efficacy of other direct targeting mAb, such as anti-CTLA-4 and anti-CD25 in a colon adenocarcinoma tumour model." (PMID 35288635, 2022). "However, its direct inhibition with anti-CTLA-4 antibodies dramatically reduced Tregs count and induced expansion of effector CD8+ T-cells at the tumor microenvironment in colon adenocarcinoma, further unveiling the therapeutic potential of targeting CTLA-4." (PMID 37605389, 2024). "Notably, higher expressions of CTLA4 and PD1 were associated with improved survival, while higher TIL load correlated with CTLA4, HAVCR2 (TIM-3), LAG3, and CD274 (PD-L1) expressions in colon adenocarcinoma." (PMID 35804964, 2022). "Finally, in the AOM/DSS-induced colonic adenocarcinoma model CD80 signaling inhibition significantly increased the frequency and extension of high-grade dysplasia, whereas enhancing CD80 activity with an anti-CTLA4 antibody significantly decreased colonic dysplasia." (PMID 25595911, 2015).
neuroblastoma (24 papers, 2015 to 2025). Neuroblastoma (NB) is the most common solid, extracranial childhood tumor. "In contrast, we found that anti-cytotoxic T lymphocyte-associated protein-4 (CTLA4) therapy increased tumor-specific T cells and was highly effective against idMMR neuroblastoma tumors." (PMID 36068918, 2023). "Poorly immunogenic neuroblastoma tumors that are refractory to immune checkpoint inhibitors can be sensitized to anti-CTLA4 with induced mismatch repair (MMR) deficiency leading to the establishment of broad immunological memory." (PMID 36068918, 2023). "Mechanistically, the effect of anti-CTLA4 therapy against neuroblastoma tumors with induced mismatch repair deficiency is CD4+ T cell dependent, as depletion of these cells abolished the effect." (PMID 36068918, 2023). "Induced MMR deficiency and anti-CTLA4 combination therapy may serve as a novel T cell-based therapy for recurrent high-risk neuroblastoma patients." (PMID 36068918, 2023). "In summary, our findings suggest that inducing MMR deficiency in neuroblastoma tumors combined with anti-CTLA4 therapy may serve as a novel potential T cell-based treatment strategy for treating high-risk neuroblastoma." (PMID 36068918, 2023). "Therefore, we show that even treatment over a relatively short time window (8 weeks) to accumulate enough immunogenic mutations in neuroblastoma tumors is sufficient to induce T cell infiltration into these poorly immunogenic tumors and sensitizes them to anti-CTLA4 treatment." (PMID 36068918, 2023). "In neuroblastoma, CTLA4 expression has been detected in both tumor cells and immune cells within the tumor microenvironment." (PMID 38542199, 2024). "The study also showed that infiltrating immune cells in the tumor microenvironment, such as T cells and macrophages, expressed CTLA4, suggesting a potential role for CTLA4 in regulating the immune response to neuroblastoma." (PMID 38542199, 2024). "Prior work from our laboratory shows that a neuroblastoma vaccine strategy containing BET/JQ1 treated cancer cells combined with anti-CTLA4 and anti-PDL-1 checkpoint inhibitors induced robust anti-tumor immunity and cured mice with established tumors." (PMID 37346042, 2023). "Our results can help justify the development of small-molecule inhibitors targeting the MMR pathway and combination treatment with anti-CTLA4 in neuroblastoma patients." (PMID 36068918, 2023). "To determine the role of CD4+ T cells on the activity of anti-CTLA4 therapy against idMMR neuroblastoma tumors, we depleted these cells in immunocompetent animals before the treatment of idMMR tumor-bearing mice with anti-CTLA4 antibody." (PMID 36068918, 2023). "We have shown that anti-CTLA4 treatment cures immunocompetent mice of established idMMR neuroblastoma tumors." (PMID 36068918, 2023). "The combination of Myc-suppressed whole tumor cells with checkpoint inhibitors targeting CTLA-4 and PD-L1 generates a potent therapeutic cancer vaccine in a mouse neuroblastoma model." (PMID 37346042, 2023). "All mice previously treated with anti-CTLA4 and cured of the immunogenic idMMR tumors rejected the less immunogenic pMMR neuroblastoma tumors." (PMID 36068918, 2023). "To assess NK cell involvement in the efficacy of anti-CTLA4 treatment against idMMR neuroblastoma tumors, we depleted NK cells in animals, then inoculated them with idMMR neuroblastoma cells and treated them with anti-CTLA4 or isotype control antibodies." (PMID 36068918, 2023). "Since tumor burden can affect the response to immunotherapy in murine models, we set up an anti-CTLA4 failure model where anti-CTLA4 was administered on a schedule that was insufficient to inhibit the growth of idMMR neuroblastoma tumors." (PMID 36068918, 2023). "In our studies, we observed an increase in CD4+ T cells in idMMR neuroblastoma tumors; therefore, we decided to treat the tumor-bearing animals with an anti-CTLA4, which mainly depends on CD4+ T cells for its effectiveness." (PMID 36068918, 2023).
neuroblastoma (continued). "When the vaccine is combined with immune checkpoint inhibitors (anti-CTLA4 and anti-PD-L1 antibodies) potent tumor specific immunity is induced in the neuroblastoma mouse model." (PMID 37346042, 2023). "To this end, we treated pMMR and idMMR neuroblastoma tumor-bearing mice with anti-CTLA4 therapy to assess T cell-based anti-tumor immune responses." (PMID 36068918, 2023). "Inhibiting PD-L1 in the context of tumor vaccination combined with another checkpoint inhibitor, anti-CTLA-4, cures established mouse neuroblastoma tumors." (PMID 29377881, 2018). "Therefore, a therapeutic strategy involving mismatch repair deficiency-based T cell infiltration of neuroblastoma tumors combined with anti-CTLA4 can serve as a novel T cell-based treatment strategy for neuroblastoma." (PMID 36068918, 2023). "Our findings demonstrate that induction of MMR deficiency in neuroblastoma tumors can sensitize them to anti-CTLA4 treatment, which primarily relies on CD4+ T cells, but not anti-PD1 treatment, which mainly depends on CD8+ T cells." (PMID 36068918, 2023). "To test whether anti-CTLA4 treatment of idMMR tumors can induce epitope spreading of T cells in cured mice, we inoculated a different cohort of animals, previously cured of idMMR tumors with anti-CTLA4, with the poorly immunogenic pMMR neuroblastoma cells." (PMID 36068918, 2023). "Importantly, our findings indicate that anti-CTLA4 treatment of idMMR neuroblastoma tumors can induce a robust T cell response involving CD8+ and CD4+ T cells." (PMID 36068918, 2023). "The combination of Id2kd-N2a cell vaccination with anti CTLA-4 plus anti PD-L1 antibody treatment proved to be highly effective, even against established neuroblastoma tumors, resulting in cure of treated mice (n = 16) as well as long-term immune memory (6 months)." (PMID 29377881, 2018). "Importantly, anti-CTLA4 treatment induced an immunological memory response with epitope spreading in cured mice, resulting in complete rejection of tumors following rechallenge with immunogenic idMMR or poorly immunogenic pMMR neuroblastoma tumors." (PMID 36068918, 2023). "We investigated chemotherapy effects on the expression of PD-L1 (PD-1), CD86 (CTLA-4), CD155 (TIGIT), and Gal-9 (TIM-3) immune checkpoint ligands by neuroblastoma cells." (PMID 36765861, 2023). "The successful treatment of cancer with inhibition of the CTLA-4, PD-1, PD-L1, and CD80/86 pathways in adults was the basis for our exploration into additional checkpoint molecule expression in neuroblastoma." (PMID 35159017, 2022). "Mouse neuroblastoma morphology and CD3+ TILs were examined following whole cell vaccination combined with CTLA-4 or PD-L1 blocking antibody." (PMID 29377881, 2018). "Therefore, we inoculated the 8-week pMMR or idMMR neuroblastoma cells into A/J immunocompetent mice and treated them with anti-PD1, anti-CTLA4, or a combination of both antibodies." (PMID 36068918, 2023). "Our findings indicate that anti-PD1 therapy uniquely induces the expression of inhibitory receptors on TILs when used against neuroblastoma tumors with induced MMR deficiency, but this is not the case with anti-CTLA4 therapy." (PMID 36068918, 2023). "Studies have also found that treatment with anti-PDL1 and/or PD-1 antibodies in concert with anti-CD4 antibody, anti-CTLA4 mAb, anti-GD2 antibody, or a CSF-R1 inhibitor can significantly decrease tumor growth compared to monotherapy alone in neuroblastoma models in vivo." (PMID 37350973, 2023). "The immune checkpoint blockade antibodies targeting CTLA4, PD-1, and PD-L1 have not influenced the clinical outcomes of neuroblastoma." (PMID 35664308, 2022). "In addition to GBM, studies have shown that a common, refractory pediatric cancer called neuroblastoma is sensitive to a combination of Prussian blue nanoparticles (PBNP) photothermotherapy (PTT) and anti-CTLA-4 checkpoint inhibitors." (PMID 36032103, 2022).
neuroblastoma (continued). "In contrast, even with the addition of anti-CTLA-4, this regimen was not effective against 9464D-GD2 neuroblastoma, which has a lower mutational burden and is more immunologically cold." (PMID 31810498, 2019). "Prior work from our laboratory showed that the aggressive nonimmunogenic mouse neuroblastoma (AgN2a) was surprisingly sensitive to Id2kd whole tumor cell vaccination and anti-CTLA-4 therapy alone." (PMID 29377881, 2018). "With the exception of a recent report suggesting CTLA-4 antibody combined with peptide antigen as an effective immunotherapy against neuroblastoma, there is no preclinical data on the role of immune-modulators in the treatment of neuroblastoma." (PMID 26079374, 2015). "Mice bearing disialoganglioside (GD2)-expressing neuroblastoma tumors (either NXS2 or 9464D-GD2) were treated with radiation and immunotherapy (including anti-GD2 immunocytokine with or without anti-CTLA-4, CpG and anti-CD40 monoclonal antibody)." (PMID 31810498, 2019).
acute myeloid leukemia (23 papers, 2012 to 2026). Acute myeloid leukemia (AML) is a group of neoplasms arising from precursor cells committed to the myeloid cell-line differentiation. "Expression of PD-1 and CTLA-4 was also observed in patients with acute myeloid leukemia (AML) and visceral adipose tissue of obese mice 179, 180, suggesting potential immunosuppression." (PMID 40860134, 2025). "Another study showed that the expression of HVEM was considerably elevated in αβ+ T cells in the low-risk group of acute myeloid leukemia (AML) patients, but CTLA-4 on γδ+ T cells and PD-1 ligand on blasts were both correlated with poor relapse-free survival in ALL patients." (PMID 38785930, 2024). "After 36-month follow-up; the subgroup of MDS patients with high expression of CD200; and high serum CTLA-4 concentrations showed high death rate and high frequency of acute myeloid leukemia transformation." (PMID 32856848, 2020). "Some recent reports showed that DNMT inhibitors (DNMTi), such as 5-azacytidine and 5-decitabine, can hypomethylate the promoter region of PD-1, PD-L2, and CTLA-4 in patients with acute myeloid leukemia with myelodysplastic syndromes (AML/MDS) and upregulate their expression." (PMID 29983831, 2018). "Acute myeloid leukemia (AML) patients have limited effect from T‐cell‐based therapies, such as PD‐1 and CTLA‐4 blockade." (PMID 35297213, 2022). "CTLA-4 overexpression has been reported in CD4+CD25+ T cells co-cultured with IDO-expressing acute myeloid leukemia (AML) cells, and this effect is completely abrogated by the IDO-inhibitor 1-methyl tryptophan (1-MT)." (PMID 36713558, 2022). "CTLA-4 expression was also evaluated in CD34+ cells from patients with myelodysplastic syndrome, chronic myelomonocytic leukemia, and acute myeloid leukemia." (PMID 31911758, 2020). "The low mutational burden of acute myeloid leukemia (AML) is one potential reason behind the lack of activity of T-cell harnessing ICIs, particularly CTLA-4 and PD-1 inhibitors." (PMID 35883692, 2022). "Interestingly, AKT is a downstream target of PP2A, a crucial serine-threonine phosphatase, which associates to CTLA-4 and regulates its inhibitory activity, and reduced PP2A activity has been related with enhanced Thr308 phosphorylation, without altering Ser473, in acute myeloid leukemia." (PMID 32850353, 2020).
endometrial cancer (23 papers, 2018 to 2026). Primary or metastatic malignant neoplasm involving the endometrium (mucous membrane that lines the endometrial cavity). "In gynecologic oncology, ICIs targeting programmed death-1 (PD-1)/programmed death-ligand 1 (PD-L1) and cytotoxic T-lymphocyte-associated protein 4 (CTLA-4) have advanced from second-line to first-line treatment for advanced/recurrent cervical and endometrial carcinomas." (PMID 41256843, 2025). "The management of advanced endometrial cancer (EC) has been transformed by immunotherapy, raising a pivotal clinical challenge: selecting patients with mismatch repair-deficient (dMMR) disease for intensive dual PD-1/CTLA-4 blockade versus standard PD-1 monotherapy." (PMID 41836431, 2026). "Immune checkpoint inhibitors targeting various immune checkpoints, such as CTLA-4, PD-1, PD-L1, and B7-H4, have been developed for endometrial cancer and have shown efficacy in improving patient survival rates." (PMID 40432915, 2025). "The immunological landscape of endometrial cancer is profoundly altered by the overexpression of multiple immune checkpoint regulators, including PD-L1, CTLA-4, TIM-3, and LAG-3." (PMID 41383623, 2025). "In endometrial cancer, PD-1/PD-L1 and CTLA-4 inhibitors tackle complex immunotherapy responses, especially in MMR-proficient, PD-L1-negative tumors." (PMID 41029427, 2025). "Immunotherapy, particularly PD-1/PD-L1 and CTLA-4 checkpoint inhibitors, has transformed gynecological cancer treatment, showing efficacy in uterine, ovarian, and endometrial cancers." (PMID 41029427, 2025). "A phase II randomized trial in patients with recurrent endometrial cancer previously treated with platinum-based chemotherapy evaluated durvalumab alone or in combination with tremelimumab (an anti-CTLA-4 agent)." (PMID 39685500, 2024). "In endometrial carcinoma, the CD4+/CD8+ TILs ratio has been reported to be significantly associated with expression of immune checkpoint proteins such as cytotoxic T-lymphocyte associated protein 4(CTLA-4) and PD-L1." (PMID 37974194, 2023). "CTLA-4 blockade has been shown to improve prognosis in endometrial cancer patients." (PMID 40356925, 2025). "Multiple ICIs against programmed cell death-1 (PD-1), programmed death-ligand 1 (PD-L1), and cytotoxic T lymphocyte-associated antigen 4 (CTLA-4) have demonstrated encouraging outcomes in controlled clinical studies for advanced cervical and endometrial cancers." (PMID 39050882, 2024). "Moreover, CTLA-4 inhibitors like ipilimumab are being investigated in combination with PD-1 inhibitors to assess their efficacy in endometrial cancer treatment." (PMID 38994352, 2024). "We are currently investigating whether anti-CTLA4 antibody is also effective in endometrial cancer." (PMID 29464025, 2018). "Previously, anti‐CTLA4 and anti‐PD‐1/PD‐L1 immunotherapies have shown limited efficacy in MSI‐H/MMR‐D endometrial cancer, leading to poor clinical outcomes." (PMID 39964147, 2025). "We performed multiplexed immunofluorescence and quantitative image analyses of CD25, FOXP3, CTLA4, and CD45RA in tumor specimens from 176 consecutive patients treated at our institution for primary endometrial carcinomas." (PMID 39232704, 2024). "We performed multiplexed immunofluorescence and quantitative image analysis for Treg markers, CD25, FOXP3, CTLA4, and CD45RA, in tumor tissues from 176 patients with endometrial carcinomas." (PMID 39232704, 2024). "First, we included the expression profile data of all normal endometrial samples and endometrial cancer samples of TCGA and observed the expression levels of common immune checkpoints, including PDCD1, CD274 (PDL1), PDCD1LG2 (PDL2), CTLA4, LAG3, and HAVCR2." (PMID 37872211, 2023). "CTLA-4 is expressed in multiple gynecologic cancers and clinical data shows that CTLA-4 blockade may enhance patient outcomes in specific endometrial cancers." (PMID 33968059, 2021).
endometrial cancer (continued). "Some scholars have found that patients with stage IV endometrial cancer with mismatch repair defects and PD-L1 negative stage show a strong clinical response to the combined inhibition of PD-1 and CTLA-4." (PMID 34124265, 2021). "Through our analysis of the TCGA dataset, we discovered that in Uterine Corpus Endometrial Carcinoma (UCEC) samples, the expression level of SLC2A1 was negatively correlated with the expression levels of CD96, CTLA-4, and PDCD-1." (PMID 40746529, 2025).
hyperthyroidism (23 papers, 2017 to 2025). Overactivity of the thyroid gland resulting in overproduction of thyroid hormone and increased metabolic rate. "Hyperthyroidism is one of the most common irAEs in the anti-PD1 or anti-CTLA4 monotherapy, which is significantly associated with the prolong of overall survival and progression free survival." (PMID 38719824, 2024). "Genotypic frequencies of CTLA4 genetic polymorphisms in the patients with hyperthyroidism and controls." (PMID 35991636, 2022). "We analysis the genotypic frequencies of CTLA4 genetic polymorphisms in hyperthyroidism patients and controls." (PMID 35991636, 2022). "The present study also showed that CTLA4 rs231775 is associated with hyperthyroidism." (PMID 34567510, 2021). "Hyperthyroidism was observed more frequently in patients treated with anti-PD1 than with anti-CTLA-4 or anti-PD-L1." (PMID 34236546, 2021).